FOXP3 (forkhead box P3)
Diseases named in the same sentence as FOXP3 in open-access papers (continued):
Sharing a sentence is not in itself a finding about the gene and the disease.
infection (continued). "In PBMCs alone, TGF-β1 and FoxP3 expression levels decreased in response to C. trachomatis infection with or without the addition of azithromycin, whereas in the presence of ECC1 cells, TGF-β1 and FoxP3 expression levels were upregulated in response to infection." (PMID 30832593, 2019). "The absence of CCR4 causes an imbalance in lung CD4+ and CD4+Foxp3+ cells, which exacerbates the Th1-mediated immune response, induces excessive pulmonary inflammation and progression of infection." (PMID 30584243, 2018). "However, following infection, the expression of FoxP3 was downregulated to levels comparable to those from wild-type mice." (PMID 29973931, 2018). "A decrease in the frequency of CD4+Foxp3+ cells was found in the lungs of infected CCR4−/− mice at 15 and 70 days of infection compared with their WT counterparts, and the number of CD4+Foxp3+ cells was significantly lower in CCR4−/− mice at 70 days of infection compared with WT mice." (PMID 30584243, 2018). "Since the lack of IL-17A leads to enlarged worms concomitant with reduced Foxp3+ Treg at the site of infection, we further analysed Th17 cell populations in the TC and mLN on day 28 p.i. using flow cytometry according to the applied gating strategy (Online Resource 5)." (PMID 29931394, 2018). "Eight to ten weeks later the Treg-inducing capacity of transplanted mLNs was analyzed so that any impact of previous infection on the frequency of de novo induced Foxp3+ Tregs could be observed." (PMID 30254319, 2018). "To begin to elucidate the mechanistic basis for the suppressive function of IFNAR-deficient Tregs during both acute and Cl-13 infection, we performed high-throughput RNA sequencing of Foxp3+ Tregs from both controls and IFNARfl/fl x Foxp3YFP-Cre mice on day 5 Armstrong and day 25 Cl-13 infection." (PMID 29672594, 2018). "Although several reports have assessed the existence of alterations of CD4+ Foxp3+ regulatory T cells during T. cruzi infection, the role of this population during the acute phase of infection still remains unclear." (PMID 28938533, 2017). "However, infection with L. infantum resulted in an increased expression of FoxP3, CD4+, TGF-β, IL-10, TNF-α and IFN-γ in the colon and jejunum and a reduction of CD8+ and IL-4." (PMID 27094260, 2017). "To determine whether this activated phenotype is correlated with a higher functional activity, we isolated CD4+ Foxp3+ Tregs from mLN at day 10 post infection and cultured them with CD4+ responder T cells." (PMID 28938014, 2017). "To achieve these goals, we investigated the co‐stimulation status of CD11b+ and CD11c+ APCs, together with Th1/Th2‐related plus Treg/Th17‐related cytokine expression levels, at the early infection stage in an experimental model with active or depleted FoxP3‐expression." (PMID 28621034, 2017). "To test whether ex-Foxp3 Th2 cells could promote immunity to H. polygyrus, we transferred ex-Foxp3 Th2 cells or conventional Th2 cells isolated from Hp 2° mice to WT Hp 1° mice and assessed luminal worm burdens 21 d after infection." (PMID 28507062, 2017). "Interestingly decrease numbers of FoxP3+ Treg cells correlates with the low degree of gastric inflammation in AM1/SS1 infection." (PMID 28286572, 2017). "Taking together, the evidence suggests that Foxp3+ Treg cells could play a beneficial role during the acute phase of infection and might coexist with a better outcome of the infection during the chronic stage." (PMID 28938533, 2017). "However, as in other tissues, there is a reduction in Foxp3+ Treg cells in the skin of naive KOCD4cre mice that persists post infection, despite a similar relative expansion in WTCD4cre and KOCD4cre mice." (PMID 28824171, 2017). "In addition to the upregulation of Th1 and Th2 markers, mRNA of the transcription factor that regulates the differentiation of Tregs, Foxp3, was transiently increased at 14 days post-infection." (PMID 28103263, 2017).
infection (continued). "Whether such redifferentiation of Foxp3+ cells occurs during immunity to infection or during Th2 cell–mediated responses is unclear." (PMID 28507062, 2017). "Using the FIV model, it has been previously demonstrated that FIV infection phenotypically and functionally activates CD4+CD25+Foxp3+ Treg cells during both the acute and chronic stages of infection and these cells are capable of inhibiting CD4+ and CD8+ T cell effector responses." (PMID 29056671, 2017). "Nevertheless, only Foxp3+ cells showed an enhanced Ki-67/Annexin V ratio following infection." (PMID 26745276, 2016). "Furthermore, we recently reported that during infection, pTregs exhibited a weak capacity to turn into an effector/memory phenotype, as they remain mainly in a naïve state loosing Foxp3 expression." (PMID 26745276, 2016). "Although most of these proteins are normally expressed exclusively with Foxp3, they may be co-expressed in certain situations such as during the course of infection." (PMID 26892542, 2016). "CCR5-dependent homing of CD4+Foxp3+ Tregs at infectious sites in parasitic pathogen infection models has been shown to promote pathogen persistence by regulating the magnitude of pro-inflammatory responses and the equilibrium between IL-17+CD4+ Th17 and CD4+Foxp3+ Tregs." (PMID 27439902, 2016). "Regulatory T cells (Tregs) expressing the forkhead box P3 (FoxP3) serve to limit the effector response to the infectious agent, which may result in a failure of infection control." (PMID 27379100, 2016). "However, PD-1 expression in Foxp3+CD4+ T cells was significantly decreased at three weeks post-infection and increased since eight weeks post-infection." (PMID 27792733, 2016). "In summary, establishing novel roles for SHH and NOTCH1 signaling pathways, we found mycobacteria-activated SHH signaling induces PD-L1 and COX-2-PGE2 to mediate the expansion of CD4+CD25+FoxP3+ Tregs whereas infection-induced NOTCH1 signaling was found to suppress the Treg expansion." (PMID 27080341, 2016). "Mechanistically, these variable outcomes of CCR5 deficiency in infectious diseases have been largely attributed to its regulatory effect on trafficking of leukocytes, including NK, CD4, CD8, and CD4+Foxp3+ Treg cells to the site of infection as a consequence of the elevated immunopathology." (PMID 27439902, 2016). "In addition, only minor changes were observed in Foxp3+ within the CD8 compartment cells after infection." (PMID 26745276, 2016). "The overrepresentation of Foxp3+ cells within the CD4 SP compartment seen during infection, conjointly with a diminished cell death, reveal that this population is more resistant to apoptosis compared to the Foxp3−CD4 thymocytes, but not enough to prevent the tTreg loss in absolute numbers." (PMID 26745276, 2016). "Strikingly, Foxp3− and Foxp3+ cell proliferations were diminished after infection." (PMID 26745276, 2016). "At 15 months post infection, strong positive correlation was revealed when parasite densities were correlated with FoxP3 transcription in both liver and skin (rs = 0.821, p = 0.023 and rs = 0.860, p = 0.019, respectively) and also TLR4 transcription in the lymph node (rs = 0.821, p = 0.023)." (PMID 26465878, 2015). "The TTR-NP mice showed a significant increase in the proportion of CD4+ FoxP3+ T cells among the CD4+ T cells after infection with LCMV-WE or LCMV-Arm compared with the B6 mice in both the spleen and liver, and they remained elevated throughout the chronic infection." (PMID 28210682, 2015). "Remarkably, numbers of T cells as well as of FOXP3+ regulatory T cells (Tregs) increased by more than twofold as early as 6 days following CCUG 30485 strain infection (p < 0.005 and p < 0.05, respectively), whereas the T cells declined thereafter to a still elevated level (p < 0.05)." (PMID 26483849, 2015).
infection (continued). "However, at week 6, the group given Treg cells displayed a more intense recruitment of macrophages and granulocytes to the site of infection than the group receiving the combination of CD4+Foxp3- T cells and Treg cells." (PMID 26512987, 2015). "During the patent phase of Schistosoma mansoni infection, Foxp3+ Treg cells are activated and suppress egg-elicited Th2 responses, but little is known of their induction and role during the early prepatent larval stage of infection." (PMID 26195548, 2015). "Instead, only CD4+ Foxp3− IL-4+ Th2 cells showed increased IL-10 production upon infection." (PMID 26195548, 2015). "In addition, an increased number of CD4+CD25+Foxp3+ cells were observed in spleen of mice with EAAI that were in the chronic phase of infection." (PMID 26114122, 2015). "Our study showed that mice infected with H. pylori PMSS1 strain have increased levels of circulating IL-10, an important mediator of Treg cell function and increased Treg cell transcription factor FoxP3 mRNA expression in their stomachs after four weeks of infection." (PMID 25807464, 2015). "In the skin, upregulation was seen only for TLR9 and FoxP3 in the early stages of infection." (PMID 26465878, 2015). "Nevertheless, all animals in both early and late depleted groups maintained low levels of infection suggesting that other cell populations contribute to the modulatory process or that in this depletion system, FoxP3+ Tregs recover sufficiently to downregulate the generation of protective immunity." (PMID 24942690, 2014). "One intraperitoneal injection of the complex immediately following infection with H. polygyrus resulted in a dramatic increase in the percentage of Foxp3+ Treg cells and increased expression of Helios on Foxp3+ T cells in the MLNCs of IL-6-deficient mice by day 7 postinfection." (PMID 24185641, 2014). "A further subset of T cells, which is prominent during H. polygyrus infection is the Foxp3+ Treg-cell population, whose suppressive function may play an important role in determining the outcome of infection." (PMID 24185641, 2014). "To check whether this expansion was analogous in M. bovis BCG infection, we first analysed the expression of FoxP3 in the CD4+ T cell population during the course of infection." (PMID 25050936, 2014). "On the contrary, CD4+CD25− T cells showed lower expression of Foxp3 mRNA during infection." (PMID 24926293, 2014). "Foxp3+ Treg were identified as CD4+GFP+ lymphocytes at different time points during infection." (PMID 24516385, 2014). "Foxp3+ Treg numbers were comparable in all strains, but in the most resistant SJL strain, this population does not upregulate CD103 in infection, and in the lamina propria the frequency of Foxp3+CD103+ T cells is significantly lower than in susceptible mice." (PMID 24492801, 2014). "Also contraction of the Foxp3+ Treg compartment to naïve levels after resolution of infection was alike." (PMID 24516385, 2014). "Both, IL-27 and Foxp3, may occur in an infection scenario induced by Fh-KTM together with other molecules with redundant suppressor functions such as GST, CL1 or HDM." (PMID 25486609, 2014). "Indeed, in contrast to Itgb8 (CD11c-Cre) mice, no enhancement of CD4+ T-cell IL-13 production was observed early during infection in Foxp3+ Treg-depleted mice." (PMID 24098124, 2013). "Therefore, we further analysed for CD4+Foxp3+ Tregs in the lungs and draining lymph nodes of pDC depleted and sham-treated mice after Cpn infection." (PMID 24386207, 2013). "However, SGE-1X treatment enhanced the number of CD4+FOXP3+ cells by three- to four-fold in the site of infection." (PMID 23656976, 2013). "Here we evaluate in detail which life-cycle stage of the worm confers protection and assess the capacity of Foxp3+ Treg induced during infection to suppress allergic airway disease by depletion Foxp3+ Treg cells in the molecularly defined DEREG (Depletion in Regulatory T cell) mouse model." (PMID 23967364, 2013).
infection (continued). "In line with the known immunomodulatory effects of H. pylori, the expression of CD-markers related to T helper (CD4/GATA4) and regulatory T cells (CD25/FOXP3) was suppressed upon an 11-month infection with H. pylori SS1, and this phenomenon was most pronounced in Cav1-KO mice." (PMID 23592983, 2013). "Moreover, our data on the presence of CD4+CD25+Foxp3+ Treg cells at the site of infection are in good agreement with ours, and others reports showing a late enhancement of Foxp3+ Treg cells associated with increased immunological responses and pathogen burden." (PMID 23936574, 2013). "Foxp3+ regulatory T (Treg) cells play central downregulatory roles in controlling reactivity to self-Ags and preventing auto-immune diseases 5, as well as in limiting inflammatory responses during infection 6,7." (PMID 23319295, 2013). "However, little is as yet known about the co-stimulatory environment in vivo which favours the differentiation and expansion of Foxp3+ Treg cells during these infections." (PMID 23319295, 2013). "Moreover, we assessed the functional role and localization of infection-induced CD4+Foxp3+ regulatory T cells (Treg) in mediating such suppressive effects." (PMID 23967364, 2013). "In fact, we found high numbers of CD4+Foxp3+GFP+ Tregs within the liver on day 7 of infection, which corroborates this hypothesis." (PMID 24312297, 2013). "It will be interesting to decipher how Treg in Inf/OVA mice are retained in the LLN and whether these are indeed infection-induced Foxp3+ T cells." (PMID 23967364, 2013). "Interestingly, when CD4+Foxp3− conventional T cells were examined for IL-35, negligible levels were found in the spleen, whereas CD4+Foxp3− T cells at the infection site had a significant increase in IL-35 expression." (PMID 24151492, 2013). "We found that infection caused reduced expression of FoxP3 and RORγ, and that fetal nonviability was associated with reduced expression of cytokines and discordant cytokine coexpression patterns." (PMID 23870389, 2013). "Also, infection with Acinetobacter baumannii ameliorates allergic airway inflammation in a Foxp3+ Treg-independent manner." (PMID 23071726, 2012). "Indeed, despite the early interruption (day 3 post-infection) of anti-CD25 administration, a sustained depletion of Foxp3+ Treg cells was detected in the lungs of both mouse strains at both post-infection periods studied." (PMID 23226464, 2012). "Thus, infection-induced reductions in maternal Foxp3+ regulatory T cell suppression with ensuing disruptions in fetal tolerance play critical roles in pathogenesis of immune-mediated fetal wastage." (PMID 22916020, 2012). "However, as was observed in this study, the enhanced migration of activated T cells and macrophages to the site of infection, which was observed only in resistant mice, was associated with anti-CD25 treatment and reduced numbers of Foxp3+ Treg cells." (PMID 23226464, 2012). "It is possible that CB4 infection in the context of TGF-β may function to stabilize Foxp3 expression and this warrants further investigation." (PMID 22355341, 2012). "Furthermore, while CD4+Foxp3− T cells numbers were similar between the two groups of mice on day 8 post infection, CD8+ effector T cell populations were elevated in the lungs of mice treated with anti-IL-10R compared to control or IgG isotype-treated mice." (PMID 22393401, 2012). "Thus, HTLV-1-infection of FoxP3+ T cells should enable the virus to increase or maintain proviral load and achieve persistent infection." (PMID 22647666, 2012). "Given the importance of expanded maternal Foxp3+ Tregs in maintaining pregnancy, and infection-induced reductions in Treg suppression that unleash immune activation in non-pregnant mice, we investigated if similar reductions in maternal Treg suppression occur with infection during pregnancy." (PMID 22916020, 2012).
infection (continued). "In addition, uninfected BALB/c mice spleens contain slightly higher basal levels of CD4+CD25+FoxP3+ cells, which transiently increased at days 2 and 4 and dropped to the base line by day 8 post-infection." (PMID 22860150, 2012). "However, we found that CD4+CD25+FoxP3+ Treg cells are rapidly induced in the periphery during acute FIV infection." (PMID 21364928, 2011). "In the present study, there was a rapid shift from a Th1 immune response characterised by the expression of IFNγ and IL-1β genes to a regulated Th2 immune response characterised by the expression of IL-13, IL-10, TGFβ, and FOXP3 genes by seven days post infection (dpi) in the carrier lambs." (PMID 21385411, 2011). "However, our results provide the first evidence that CD4+CD25+FoxP3+ regulatory T cells (Treg), which have the capacity to suppress Th1 effector responses and favor Leishmania survival, are recruited to the infection sites in L. braziliensis-infected mice." (PMID 21390155, 2011). "A pronounced increase in the proportion of CD4+FoxP3+Tregs within colonic granulomas at the chronic phase of infection, from 2.9±0.6% to 18.8±0.7% was revealed by enumeration of double positive versus single positive cells in anti-CD4 / anti-FoxP3 immunostained cryosections of colonic tissue." (PMID 21858239, 2011). "Such increase in the absolute number of circulating FOXP3+ Treg cells might be driven as a direct consequence of the infection." (PMID 22087344, 2011). "Whereas there was a clear association between increases in Th1 cells and Tregs in the UGT, such a pattern was not as clear for the LGT, as the RT-PCR detection revealed only 6-fold increases in FoxP3 mRNA in the LGT as compared to nearly 40-fold increases in the UGT over the course of the infection." (PMID 21079691, 2010). "In this study, the role of Foxp3+ Tregs in controlling immune cell activation and the balance between pathogen proliferation and clearance during the natural progression of persistent bacterial infection was examined after infection with virulent Salmonella." (PMID 20714351, 2010). "Therefore, additional studies using representative mouse models of other human infections and Foxp3-specific reagents for Treg manipulation are required." (PMID 20714351, 2010). "Along with two recent studies characterizing infection outcome with Foxp3+ Treg ablation after mucosal HSV-2, systemic LCMV, and footpad West Nile virus infections, these are the first studies to characterize the importance of Tregs during infection using Foxp3DTR transgenic mice." (PMID 20714351, 2010). "There was a slightly increased representation of FoxP3+ Treg during infection, whether it was CIA mice alone or Sj infection with CIA mice." (PMID 20537152, 2010). "Interestingly, for FliC431–439-specific CD4+ cells identified in this manner, ∼10% were Foxp3+ in F1 mice prior to and at each time point after infection." (PMID 20714351, 2010). "Since IL-2Jc treatment increased IL-10 and CTLA-4 expression by Foxp3+ CD4+ T cells during infection, we hypothesized that protection was dependent upon these two molecules." (PMID 21170302, 2010). "However, the percentage of CD4+CD25+Foxp3+ T cells increased significantly after the infection, following the same pattern seen in suckling mice." (PMID 19319188, 2009). "In this study, FoxP3+ T cells in PTs expressed an activated (Ki67+) phenotype and were increased at later time points following infection, consistent with the induction of an adaptive Treg response that exerted limited, if any, suppression of T cell activation in the periphery." (PMID 19214220, 2009). "Association between multiplicity of infection of HIV-1 (BaL) required for the 50% inhibitory effect of PBMC (Infectivity) and the proliferative response, percentage of IFNγ produced and CD25+FoxP3+ T cells (T regs) of CD4+ T cells; analysis by Mann Whitney test." (PMID 19956755, 2009).